RTN2 (reticulon 2)
Description:
Inhibits amyloid precursor protein processing, probably by blocking BACE1 activity. Enhances trafficking of the glutamate transporter SLC1A1/EAAC1 from the endoplasmic reticulum to the cell surface (By similarity). Plays a role in the translocation of SLC2A4/GLUT4 from intracellular membranes to the cell membrane which facilitates the uptake of glucose into the cell (By similarity).
Synonyms: NSPLI; NSPL1; NSP2; HMNR11; SPG12
Tractability: Antibody: UniProt places it where antibodies can reach, with medium confidence; UniProt predicts a signal peptide or a membrane-spanning region; its Gene Ontology location is reachable by antibodies, with medium confidence. PROTAC: its protein half-life has been measured.
Gene: Protein-coding gene on chromosome 19 (45,485,294 to 45,497,055, reverse strand). Ensembl gene ENSG00000125744.
Subcellular location: Endoplasmic reticulum membrane; Sarcoplasmic reticulum membrane; Cell membrane; Cell membrane, sarcolemma; Cell membrane, sarcolemma, T-tubule; Cytoplasm, myofibril, sarcomere, Z line; Cytoplasm, cytoskeleton
Subcellular location (Human Protein Atlas): Vesicles
Gene Ontology:
Molecular function: protein binding
Biological process: negative regulation of amyloid-beta formation; brain development; endoplasmic reticulum tubular network formation; endoplasmic reticulum tubular network membrane organization; intracellular protein transmembrane transport; neuron differentiation; regulation of D-glucose import
Cellular component: endoplasmic reticulum; endoplasmic reticulum membrane; intermediate filament; neuron projection; plasma membrane; postsynaptic density; sarcoplasmic reticulum membrane; T-tubule; terminal cisterna; Z disc; cell surface; cytoskeleton; sarcolemma
Genetic constraint (gnomAD): Loss-of-function variants: 34 observed, 60.51 expected, observed/expected ratio (o/e) 0.56, 90% interval 0.43 to 0.75. The upper end of that interval is the gene's LOEUF score, 0.75, which puts it in group 3 of 6, group 1 being the genes least tolerant of losing a copy. Missense variants: 661 observed, 715.36 expected, observed/expected ratio (o/e) 0.92, 90% interval 0.87 to 0.99. Synonymous variants: 304 observed, 318.52 expected, observed/expected ratio (o/e) 0.95, 90% interval 0.87 to 1.05.
Homologues: Orthologues: chimpanzee RTN2 (99% identical), macaque RTN2 (84% identical), rabbit RTN2 (75% identical), dog RTN2 (74% identical), pig RTN2 (73% identical), mouse Rtn2 (72% identical), guinea pig RTN2 (71% identical), rat Rtn2 (69% identical), tropical clawed frog rtn2 (24% identical), Drosophila melanogaster Rtnl1 (22% identical), zebrafish rtn2b (14% identical), Drosophila melanogaster Rtnl2 (11% identical). Paralogues in human: RTN1 (29% identical), RTN4 (26% identical), RTN3 (23% identical), PRR18 (6% identical).
Diseases named in the same sentence as RTN2 in open-access papers:
RTN2 is named in the same sentence as 25 diseases in open-access papers, as found by Europe PMC text mining. Sharing a sentence is not in itself a finding about the gene and the disease. The quoted sentences say what the papers report.
hereditary spastic paraplegia (5 papers, 2017 to 2024). Hereditary spastic paraplegias (HSP) comprise a genetically and clinically heterogeneous group of neurodegenerative disorders characterized by progressive spasticity and hyperreflexia of the lower limbs. "Mutations in ER-shaping proteins such as Spastin, ATL1, RTN2 or REEP1 that couple the tubular ER network with microtubule dynamics cause hereditary spastic paraplegia." (PMID 35650592, 2022). "Heterozygous RTN2 variants have previously been associated with progressive hereditary spastic paraplegia (HSP) (SPG12-MIM#604805).2,3 However, this association is yet to be confidently established." (PMID 38527963, 2024). "ATL1, RTN2, SPAST and REEP1 are the causative genes of hereditary spastic paraplegia (HSP)." (PMID 29310658, 2018).
autosomal dominant spastic paraplegia (2 papers, 2020 to 2024). "Heterozygous RTN2 variants have been previously identified in a limited cohort of families affected by autosomal dominant spastic paraplegia (SPG12-OMIM:604805) with a variable age of onset." (PMID 38527963, 2024).
colon cancer (2 papers, 2021 to 2023). "Thus, we speculated that RTN2 could act as an anticancer target and a biomarker for the prognosis of colon cancer." (PMID 34421995, 2021). "In this work, we retrospectively identified four bone metastasis-related genes (INHBB, RBP7, RTN2, and ATOH1) and constructed a gene expression signature model for colon cancer patients by bioinformatic analysis." (PMID 34421995, 2021). "The spatial cellular expression patterns of RTN2 have not been investigated in colon cancer, but RTN2 expression was found to be positively correlated with degenerative disorder." (PMID 34421995, 2021).
gastric cancer (2 papers, 2022 to 2025). A primary or metastatic malignant neoplasm involving the stomach. "We next evaluated the association between RTN2 expression and clinicopathological features in gastric cancer patients." (PMID 35428758, 2022). "Besides, high RTN2 staining intensity was associated with adverse survival which was further identified as an independent prognostic factor for gastric cancer patients by multivariate analysis." (PMID 35428758, 2022). "And IHC data clarified that upregulation of RTN2 was positively associated with tumour progression and could be regarded as a potential unfavourable prognostic marker for gastric cancer patients." (PMID 35428758, 2022). "Confocal imaging displayed that more and larger paxillin clusters were detected in RTN2-overexpressed gastric cancer cells." (PMID 35428758, 2022). "As RTN2 expression was related to tumour invasion depth in gastric cancer patients, the effects on cell migration and invasion were investigated." (PMID 35428758, 2022). "In conclusion, our work revealed that high RTN2 expression was an independent and adverse predictor of overall survival in gastric cancer patients." (PMID 35428758, 2022). "Among the members of the reticulon family, only RTN2 mRNA level was statistically significantly increased in gastric cancer tissues and displayed a similar tendency in all datasets." (PMID 35428758, 2022). "The results indicated that blockade of cytosolic calcium by BAPTA-AM reversed RTN2-induced ERK/Snail signalling activation as well as the migration of gastric cancer cells." (PMID 35428758, 2022). "In this study, we analysed RTNs expression in paired gastric cancer samples from different reported datasets and found that RTN2 mRNA level was coincidently upregulated in tumour tissues compared with non-tumour tissues." (PMID 35428758, 2022). "Tissue microarray was used to determine the expression levels of RTN2 in 267 gastric cancer patients by immunohistochemistry." (PMID 35428758, 2022). "Meanwhile, elevated expression of RTN2 was identified as an independent factor that contributed to the poor prognosis in gastric cancer patients." (PMID 35428758, 2022). "Given previous studies that ER-resident reticulons were closely related to ER Ca2+ flux, and intracellular Ca2+ was critical for the activation of ERK, we evaluated the effect of RTN2 on ER Ca2+ release in gastric cancer cells." (PMID 35428758, 2022). "In vivo and in vitro studies also indicated that RTN2 promoted the proliferation, epithelial-to-mesenchymal transition and metastatic potential in gastric cancer cells." (PMID 35428758, 2022). "Next, we combined RTN2 expression with TNM-staging system to construct a more accurate predictive model for outcomes of gastric cancer patients." (PMID 35428758, 2022). "In this study, we found that reticulon 2 (RTN2) was upregulated in gastric cancer, and overexpression of RTN2 promotes migration and invasion of tumour cells." (PMID 35428758, 2022). "Gastric cancer cell lines were utilised to examine the influences of RTN2 on cellular migration and invasion abilities, epithelial-to-mesenchymal transition (EMT) and signalling pathway." (PMID 35428758, 2022). "Then Kaplan–Meier analysis was used to evaluate the correlation between intratumoural RTN2 expression and overall survival of gastric cancer patients after gastrectomy." (PMID 35428758, 2022). "Furthermore, RTN2 overexpression significantly facilitated the viability and colony-formation ability of gastric cancer cells, while RTN2 knockdown exhibited opposite effects." (PMID 35428758, 2022). "RTN2 could promote the proliferation, migration and invasion of gastric cancer cells in vitro and lung metastasis in vivo." (PMID 35428758, 2022). "Hence, these findings imply that the pro-metastatic impacts of RTN2 in gastric cancer is ERK-dependent." (PMID 35428758, 2022).
gastric cancer (continued). "Our present results might provide clues towards a better understanding of the pro-tumour functions of IP3R in gastric cancer, which could be promoted by RTN2 to stimulate downstream ERK signalling." (PMID 35428758, 2022). "Nevertheless, our study demonstrated that the mRNA levels of RTN2 were increased in gastric cancer, suggesting that RTN2 might be transcriptionally upregulated during gastric tumorigenesis." (PMID 35428758, 2022). "Conversely, RTN2 depletion impaired the peritoneal metastatic ability of gastric cancer cells." (PMID 35428758, 2022). "Furthermore, we also utilised stable RTN2 overexpression or knockdown gastric cancer cells to establish an animal model of peritoneal metastasis." (PMID 35428758, 2022). "Herein, we explored the potential role of reticulon 2 (RTN2) in the progression of gastric cancer." (PMID 35428758, 2022). "Similarly, high expression of RTN2 was correlated with depressed overall survival in both subgroups of gastric cancer patients." (PMID 35428758, 2022). "Taken together, incorporation TNM staging system and RTN2 expression could create a more mightily predictive model for the overall survival of patients with gastric cancer." (PMID 35428758, 2022). "Therefore, a tissue microarray was employed to examine the protein expression of RTN2 in 267 gastric cancer patients with different stages by immunohistochemical analysis." (PMID 35428758, 2022). "Transwell assays demonstrated that both gastric cancer cells exhibited a higher migratory and invasive potential when RTN2 was overexpressed, while the migratory and invasive abilities were impaired when RTN2 was knocked down." (PMID 35428758, 2022). "In this study, we found that RTN2 expression was increased in gastric cancer." (PMID 35428758, 2022). "To further explore the molecular mechanism responsible for the accelerative function of RTN2 in gastric cancer metastasis, we first performed KEGG pathway enrichment analysis to identify potential signalling pathways associated with RTN2 using the TCGA-STAD database." (PMID 35428758, 2022). "RTN2 could promote lung metastasis of gastric cancer cells in vivo." (PMID 39972424, 2025). "Thus, RTN2 might represent a new biomarker for gastric cancer prognosis and targeting RTN2 may provide a novel approach for the treatment of gastric cancer." (PMID 35428758, 2022). "It implied that RTN2 might play an important role in the development of gastric cancer." (PMID 35428758, 2022). "Together, these results suggest that RTN2 enhances EMT and the development of focal adhesion in gastric cancer cells." (PMID 35428758, 2022). "We next investigated the potential function of RTN2 in tumour characteristics in human normal gastric epithelial cell line GES-1 and two kinds of human gastric cancer cell lines including MGC80-3 and AGS." (PMID 35428758, 2022). "In this study, our results demonstrated that RTN2 promotes proliferation, migration, invasion and EMT in gastric cancer cells in vitro through ER Ca2+ efflux-mediated ERK activation." (PMID 35428758, 2022). "Similar to gastric cancer cells, the number of migratory and invasive GES-1 cells were increased or reduced along with RTN2 overexpression or depletion, respectively." (PMID 35428758, 2022). "Furthermore, RTN2 could also accelerate metastasis of gastric cancer cells in vivo, implying that the enhanced proliferation of gastric cancer cell benefits for its survival in circulation, extravasation efficiency and the efficiency of tumour cells outgrowth in the lung." (PMID 35428758, 2022). "RTN2 promoted ER Ca2+ release, and subsequently activated the ERK signalling pathway which droved EMT and led to the metastasis of gastric cancer cells." (PMID 35428758, 2022). "However, the effects of RTN2 on other channels including SERCA2, STIM and ORAI were marginal or inconsistent between the two gastric cancer cells." (PMID 35428758, 2022).
gastric cancer (continued). "Mechanistically, RTN2 interacted with IP3R, and activated ERK signalling pathway via facilitating Ca2+ release from the endoplasmic reticulum, and subsequently drove EMT in gastric cancer cells." (PMID 35428758, 2022). "Therefore, RTN2 could promote ER Ca2+ efflux through upregulating IP3R, leading to the ERK activation as well as tumour migration and invasion of gastric cancer cells." (PMID 35428758, 2022).
autosomal dominant spastic paraplegia 12 (1 paper, 2014). "The evidence that mutations in the RTN2 gene cause the autosomal dominant spastic paraplegia 12 (SPG12) was very recently demonstrated by our group." (PMID 24218324, 2014).
distal hereditary motor neuropathy (1 paper, 2024). "In this study, we identified and validated seven novel or ultra-rare homozygous loss-of-function RTN2 variants in 14 individuals from seven consanguineous families with distal hereditary motor neuropathy (dHMN) using exome, genome and Sanger sequencing coupled with deep-phenotyping." (PMID 38527963, 2024).
distal motor neuropathy (1 paper, 2024). "Here, we identified 14 individuals from seven independent consanguineous families with homozygous loss-of-function (LoF) RTN2 variants presenting with slowly progressive distal motor neuropathy with spasticity and hyperreflexia affecting the upper and lower limbs." (PMID 38527963, 2024).
epilepsy (1 paper, 2015). A brain disorder characterized by episodes of abnormally increased neuronal discharge resulting in transient episodes of sensory or motor neurological dysfunction, or psychic dysfunction. "RTN2, also a VIP in E-DE network module C, is a regulator of the glutamate transporter EAAC1; the dysregulation of EAAC1 was reported in animal models of epilepsy and in the hippocampus of TLE patients." (PMID 26011637, 2015).
lymph node metastasis (1 paper, 2022). "Chi-square analysis revealed that high expression of RTN2 was positively correlated with older age (P = 0.009), more vessel invasion (P = 0.018), tumour invasion depth (P = 0.030), lymph node metastasis (P = 0.026) and advanced TNM (tumour node metastasis) stage (P = 0.012)." (PMID 35428758, 2022).
Obesity (1 paper, 2014). Accumulation of substantial excess body fat. "To test transcriptional effects of miR-125a down-regulation in human obesity, we quantified the expression of its target genes Tef, Masp1, Rtn2, Ube2l3 and Adam9 in subcutaneous adipose tissue samples of obese patients." (PMID 24675842, 2014). "More specifically Masp1, Tef, Rtn2 and Ube2l3 showed contrasting expression patterns before and after gastric bypass but the effects were statistically significant for Tef only, which highlights a possible specific role of Tef in obesity and IR of obese patients." (PMID 24675842, 2014).
osteoarthritis (1 paper, 2023). A noninflammatory degenerative joint disease occurring chiefly in older persons, characterized by degeneration of the articular cartilage, hypertrophy of bone at the margins and changes in the synovial membrane. "For example, we found that all measures of adiposity have a causal effect on higher expression of IRX3 in synovium or pancreatic islets and on lower expression of RTN2 in osteoarthritis cartilage." (PMID 37433298, 2023).
infection (1 paper, 2024). The state of being infected such as from the introduction of a foreign agent such as serum, vaccine, antigenic substance or organism. "On day 5 post infection, the body weight loss in the groups of rtN2(×3), rtN2/N2P2-KLH(×2), and rtN2/N2P2TP2nano(×2) were comparable and significantly slower than that of the other groups." (PMID 38257777, 2024).
neurological diseases (1 paper, 2018). "Interestingly, mutations in genes involved in the regulation of ER biogenesis and maintenance, such as Valosin-containing protein (VCP), Atlastin-1 (ATL1), Spastin (SPAST), Reticulon 2 (RTN2), and Receptor expression enhancing protein 1 (REEP1) have been linked to neurological diseases." (PMID 29310658, 2018).
tumour (1 paper, 2022). "We found that RTN2 expression was notably upregulated in tumour tissues compared to pericarcinomatous tissues." (PMID 35428758, 2022). "High RTN2 expression was positively correlated with patients’ age, vessel invasion, tumour invasion depth, lymph node metastasis and TNM stage." (PMID 35428758, 2022). "Nevertheless, nude mice inoculated with RTN2 shRNA-transfected MGC80-3-luciferase cells exhibited weak luminescent tumour signal compared with those inoculated with control cells." (PMID 35428758, 2022). "Further statistical analysis demonstrated that the RTN2 staining score in tumour cells was remarkably higher compared to that in the normal gastric epithelium." (PMID 35428758, 2022). "In vivo studies were also performed to detect the effect of RTN2 on tumour metastasis." (PMID 35428758, 2022). "RTN2 overexpression remarkably enhanced luminescent tumour signal in nude mice." (PMID 35428758, 2022).
RTN2 also shares sentences with these, for which no sentence is quoted: amyotrophic lateral sclerosis (1 paper); Ataxia (1); autosomal dominant spastic paraplegia 3A (1); autosomal dominant spastic paraplegia 4 (1); febrile seizures (1); frontotemporal dementia (1); neurodegenerative disease (1); Parkinson disease (1); staphylococcus aureus infection (1); temporal lobe epilepsy (1); Troyer syndrome (1).